INS (insulin)
Diseases named in the same sentence as INS in open-access papers (continued):
Sharing a sentence is not in itself a finding about the gene and the disease.
Insulin resistance (continued). "Any abnormalities in insulin signaling pathways may cause reduction of its sensitivity, as a result of insulin resistance." (PMID 31071176, 2019). "Interestingly, numerous studies clearly reported that chronic exposure to high leptin levels, which mimics obesity-associated hyperleptinemia, promotes hypothalamic insulin resistance through the impairment of neuronal insulin signaling." (PMID 30906281, 2019). "This may be due to insulin resistance and abnormities of insulin secretion, both generally caused by age." (PMID 31096476, 2019). "Furthermore, glucose and insulin tolerance test studies indicated that obesity associated insulin resistance were exacerbated upon HFD feeding." (PMID 31477775, 2019). "Insulin resistance in classic insulin-responsive tissues is a hallmark of type 2 diabetes (T2D)." (PMID 31311313, 2019). "In recent studies, hippocampal insulin has been proposed to regulate cognitive functions, and obesity leads to impairments in hippocampus-dependent behavior that is caused by hippocampal insulin resistance." (PMID 31311133, 2019). "This evidence raised the idea that insulin resistance may provoke a loss of insulin-mediated control of GLUT2 membrane trafficking, leading to unleash intestinal glucose absorption upon high-sugar diets consumption." (PMID 31905727, 2019). "In the context of a well-established limited insulin secretion in adult CF patients, three key factors could contribute to the development of hyperglycemia: progression of insulin secretory deficiency, higher insulin resistance or higher insulin requirements." (PMID 30894563, 2019). "In addition, disruption of MAMs by FATE-1 blunted the impact of NO on insulin signaling, causing insulin resistance." (PMID 31731523, 2019). "These factors are known to influence insulin sensitivity, suggesting that insulin resistance, in addition to insulin deficiency due to autoimmune destruction of the beta cells, may play a key role in the pathogenesis of LADA." (PMID 30971952, 2019). "This may be because insulin acts as a co-gonadotrophin to stimulate ovarian androgen production, and thus hyperinsulinaemia and the severity of insulin resistance is associated with increased circulating androgen concentrations." (PMID 31097035, 2019). "In conclusion, this study showed that glutamate excitotoxicity is causative for central insulin resistance and may induce the acute loss of insulin signalling within minutes under mitochondrial depolarisation conditions." (PMID 31856878, 2019). "Insulin resistance is an intricate metabolic condition, which causes insensitivity to insulin, as well as its downstream metabolic actions under normal serum glucose concentrations to the three metabolic tissues, i.e., liver, skeletal muscle, and white adipose tissue." (PMID 31597283, 2019). "As catecholamines are widely known to reduce peripheral insulin-sensitive glucose uptake and to increase insulin resistance, these findings strongly suggest that IH causes insulin resistance in peripheral organs/tissues via the increased release of catecholamines from sympathetic neural system." (PMID 31557884, 2019). "LPS also promotes the activation of the nuclear factor kappa-B (NFkB) and c-Jun N-terminal kinase (JNK) pathways, both of which have been linked to the development of insulin resistance and impaired insulin signalling in muscle, adipose tissue, liver, and hypothalamus." (PMID 30987356, 2019). "However, there is strong evidence in animals and humans to support a causal role of excess insulin in driving insulin resistance, and that suppression of high plasma insulin levels enhances insulin action." (PMID 31489455, 2019). "Evidences of the involvement of insulin signaling on brain mechanisms related to depression indicate that insulin resistance, a hallmark of type 2 diabetes, could develop in the brains of depressive patients." (PMID 30837902, 2019).
Insulin resistance (continued). "Insulin resistance is classically defined as the state in which high levels of circulating insulin (hyperinsulinemia) are associated to hyperglycemia, concept that has been extended to other tissues and organs which show reduced activation of the pathways in insulin signaling." (PMID 31551756, 2019). "Declined adiponectin level causes a reduced response to the insulin action what indicates that the adiponectin may become a way of treatment of insulin resistance and T2DM." (PMID 31496996, 2019). "Mixed evidence emerged that more-intensive interventions were associated with improved glucose regulation and insulin resistance, because several estimates were imprecise and CIs for insulin and insulin resistance included the null (eFigures 1.1-1.4 in the Supplement)." (PMID 31260026, 2019). "LCD may effectively control body weight in overweight or obese people, lower insulin levels, and improve insulin resistance and other endocrine deficiencies." (PMID 31885557, 2019). "However, the association between insulin use and mortality will be strongly influenced by the severity of disease, which will result in higher insulin resistance." (PMID 30742240, 2019). "Human and animal model studies revealed that AD is associated with reduced insulin levels in the CSF and with insulin resistance, as well as with lower levels of the insulin receptor substrate IRS1 and higher levels of p-IRS1, which is a marker of brain insulin resistance." (PMID 30890171, 2019). "It is also suggested that inhibitory interplay between leptin and insulin signaling in the hypothalamus could have a causal role in the onset and the progression of hypothalamic insulin resistance." (PMID 30906281, 2019). "This could be caused by impaired insulin sensitivity and suggests that nesfatin-1 might be inhibited by insulin resistance, hyperglycemia, and hyperinsulinemia." (PMID 30621139, 2019). "The present model has not been modified to include a direct effect of insulin on β-cells, also because we agree with the statement that the required causal signal linking insulin resistance and insulin hypersecretion may well be glycemia itself." (PMID 31600232, 2019). "Elderly cancer patients with insulin resistance may be at a high risk for developing cognitive impairment, which may be prevented by early treatment that reduces insulin sensitivity." (PMID 31661025, 2019). "Insufficient insulin production/secretion by the pancreatic beta cells and insulin resistance are two leading pathological causes of T2DM; therefore, these abnormalities are associated with defects in glucose uptake and glucose homeostasis, which can cause hyperglycemia." (PMID 32133058, 2019). "Interestingly, the metabolic measures which showed blunted changes in insulin-resistant individuals in this study have been also associated with insulin resistance in the fasting state." (PMID 31779625, 2019). "Deficiency in PFK is associated with impaired insulin secretion and insulin resistance in human." (PMID 29315239, 2018). "However, we observed increased rates of insulin resistance, with higher levels of basal insulin and HOMA-IR in PKU patients, associated with age, BMI, and WC, suggesting possible alterations in glucose homeostasis." (PMID 29945661, 2018). "Insulin resistance is associated with reduced hepcidin synthesis and it may lead to increased body iron stores in insulin resistant cases." (PMID 29949646, 2018). "The supplementation with O. tenuiflorum capsules (250 mg twice daily for 8 weeks) decreased plasma insulin and insulin resistance by 28.49% and 24.79% respectively, caused the normalization of serum lipid profile, and reduced body weight and BMI, compared to the control group (no intervention)." (PMID 29300317, 2018).
Insulin resistance (continued). "The PI3K/Akt signaling pathway, which is an insulin downstream molecular pathwayclosely associated with the development of insulin resistance, plays a vital role invarious biological processes such as glucose transport, cell cycle regulation, cellmetabolism, cell growth, and apoptosis." (PMID 29924135, 2018). "Both progress through stages of insulin resistance with hyperinsulinemia, leading to beta cell failure, and finally to severe hyperglycemia characterized by inadequate insulin production and insulin deficiency associated with ketoacidosis resulting in adipose and muscle-wasting disease." (PMID 29463026, 2018). "Type 2 diabetes is caused either by a loss of insulin secretion or insulin resistance." (PMID 30205460, 2018). "High amounts of fat in the abdomen as well as ectopic depots have been linked to insulin resistance and metabolic diseases and may impair insulin action in other organs." (PMID 30377436, 2018). "Insulin resistance can also impact tissues of the joint organ system, because insulin resistance has been linked to chondrocyte dysfunction, and insulin appears to have a protective role for synoviocytes, whereby insulin blunts TNF-induced matrix metalloproteinase release." (PMID 29527173, 2018). "After five months, rats exposed to Cd presented a greater metabolic disorder, showing evidence of zoometric worsening as well as lipid and glucose homeostasis in both serum and tissues, with a marked development of insulin resistance and loss of hepatic insulin sensitivity." (PMID 30201894, 2018). "Since there is a strong direct correlation between insulin resistance and hyperuricemia, decreased insulin resistance and insulin levels associated with coffee consumption may lead to lower uric acid levels." (PMID 29937486, 2018). "Glucose tolerance is associated with insulin resistance and insulin secretion." (PMID 30041479, 2018). "Considering the fact that androgen excess could be caused by either insulin resistance or hyperprolactinemia, we decided to treat one sister with insulin sensitizer metformin and other with dopamine agonist cabergoline." (PMID 30250766, 2018). "In an insulin-dysregulated horse hyperinsulinemia can manifest as pulsatile, post-prandial spikes in circulating insulin, or in the development of persistent hyperinsulinemia, which may be associated with insulin resistance." (PMID 29958298, 2018). "However, insulin sensitivity and glucose tolerance were maintained, likely owing to an increased conversion of saturated fatty acids (known to cause insulin resistance) to monounsaturated fatty acids mediated by stearoyl-CoA desaturase-1 (SCD1)." (PMID 29936596, 2018). "In fact, specific ablation of M1-like macrophages restores insulin sensitivity and liver lipid levels in diet-induced obese mice, while deleting Pparδ, which promotes M2 polarization, thereby predisposing lean mice to develop insulin resistance." (PMID 29599925, 2018). "While the exact cause of insulin resistance is unknown, there are multiple factors that can contribute to the reduced insulin sensitivity of target cells, including genetic and lifestyle factors." (PMID 29601521, 2018). "Furthermore, we uncovered a novel mechanism whereby dysregulated miR199a-5p suppresses the expression of ATG14 and inhibits autophagy, which in turn leads to the downregulation of hepatic insulin sensitivity and eventually causes insulin resistance." (PMID 29540751, 2018). "In a nutritional model obesity associated with insulin resistance, sage MetOH extract reduces bodyweight gain by a decrease in total fat mass and exhibits anti-diabetic properties by an improvement of glucose tolerance and insulin sensitivity." (PMID 29333341, 2018). "Additionally, similar to our findings, other studies also observed association of AA genotype with insulin levels and insulin resistance index." (PMID 29854435, 2018).
Insulin resistance (continued). "The discrepancy in the effects of BCAAs in insulin response may be due to the difference in the role of moderate intake of dietary BCAAs and pathogenic metabolic pathways related to insulin resistance, manifesting as increased circulating BCAA levels." (PMID 29632321, 2018). "Endothelial dysfunction is usually indicated by decreased bioavailable NO in response to acetylcholine/insulin mediated vascular relaxation or impaired flow mediated vasodilation, is strongly associated with insulin resistance and hyperglycemia in diabetes mellitus." (PMID 29669555, 2018). "It has been reported that compared with lean controls, adipose tissues of the obese individuals secrete elevated levels of inflammatory cytokines such as tumor necrosis factor- (TNF-) α and interleukin- (IL-) 6, which impair insulin signaling and cause insulin resistance." (PMID 30123267, 2018). "PPARγ activation enhances insulin sensitization in skeletal muscle and increases glucose metabolism and adipogenesis in white and brown fat tissue, cause-effect relationship between insulin resistance and the stimulation of muscle protein breakdown." (PMID 30647761, 2018). "Moreover, they showed increased insulin resistance, which underlied defects on the insulin signaling cascade." (PMID 30429829, 2018). "In addition, recent studies have described that acute activation of AgRP neurons can cause insulin resistance through an impairment of the insulin-stimulated glucose uptake into brown adipose tissue (BAT)." (PMID 32232085, 2018). "Acute pancreatic necrosis (APN) occurs due to predisposing factors such as insulin antagonism, insulin resistance, alteration in glucose tolerance, obesity, hyperadrenocorticism, and persistent usage of glucocorticoids, as these play a vital role in the progression of APN." (PMID 29805204, 2018). "Since decreased fatty acid oxidation is associated with the development of insulin resistance, the metformin-induced fatty acid oxidation might contribute to the increase of insulin sensitivity." (PMID 30034573, 2018). "Insulin resistance, closely linked to obesity, occurs when cells are less responsive to insulin." (PMID 30108548, 2018). "This is implying that a low ponderal index is linked to an increased insulin secretion in adulthood, which could be a compensatory mechanism in response to insulin resistance, thus, it is also in accordance with the fetal insulin hypothesis." (PMID 30514227, 2018). "Interestingly, under insulin resistance (overt T2D) or impaired insulin secretion (late T2D)-associated conditions, the growth promoting actions by adipocytes were further increased." (PMID 30524378, 2018). "Moreover, ANGPTL8 induces pancreatic β-cell proliferation and insulin release in an insulin-deficient mouse model of insulin resistance." (PMID 29389861, 2018). "In the Tuebingen Lifestyle Intervention Program (TULIP), a high-risk phenotype was identified that displayed low insulin secretion relative to insulin resistance or insulin resistant non-alcoholic fatty liver disease, and a low-risk phenotype was an individual without these traits." (PMID 30128932, 2018). "Interestingly, selective depletion of fTreg cells increases adipose tissue insulin sensitivity implicating these cells as drivers of age-associated insulin resistance." (PMID 29867762, 2018). "Lifestyle factors linked to insulin resistance such as high serum levels of insulin and IGF-I, abdominal adiposity, high energy intake, milk consumption and low levels of physical activity have in fact been associated with higher penetrance of BC in BRCA mutation carriers." (PMID 30181513, 2018). "T2DM is linked to insulin resistance and a loss of insulin sensitivity." (PMID 30314325, 2018). "Vaspin is an adipokine with insulin- sensitizing effects, and may be involved in obesity-associated diseases including type 2 diabetes, insulin resistance, atherosclerosis and cardiovascular disease." (PMID 29670847, 2018).
Insulin resistance (continued). "In humans, dominant negative PPARγ mutations are associated with obesity, dyslipidemia, and severe insulin resistance, whereas a common polymorphism (Pro12Ala) has been shown to decrease PPARγ receptor activity, improve insulin sensitivity, and decrease T2DM risk." (PMID 29747466, 2018). "To assess whether this systemic improvement in insulin resistance caused by EA also extends to hepatic tissue, we evaluated the activation of Akt, a key molecule in the insulin signaling pathway." (PMID 29693586, 2018). "In this review, we summarize recent advances in the understanding of the functions of Sirtuins in various insulin resistance-associated physiological processes, including inflammation, mitochondrial dysfunction, the insulin signaling pathway, glucose, and lipid metabolism." (PMID 30574122, 2018). "One could speculate that fasting glucose, TGs, and NEFA might reflect insulin resistance, while lower C-peptide levels associate with a dysfunction of insulin secretion." (PMID 29615972, 2018). "The main causes of T2DM are insulin resistance and/or inadequate insulin secretion." (PMID 30558294, 2018). "Previous studies reported that higher fasting serum insulin and insulin resistance may be associated with higher risk of lower BMD and lower femoral neck strength." (PMID 30083134, 2018). "On the other hand, medication leading to improved insulin sensitivity could have beneficial effects on cognitive function, which reflects the association between insulin resistance and impaired cognitive function, observed in some studies." (PMID 30159333, 2018). "Aging mice with depletion of adipose Treg exhibited increased insulin sensitivity compared to control mice, suggesting that Treg in adipose tissue may play a detrimental role in age-associated insulin resistance." (PMID 30619305, 2018). "Any defects in the insulin signaling cascade can cause insulin resistance." (PMID 30524482, 2018). "Variants in TCERG1L have been shown to be associated with fasting insulin and insulin resistance in an African–American population, which could have implications for growth of both the mother and the offspring." (PMID 28990592, 2018). "PERK transiently inhibits eukaryotic initiation factor (EIF-2α) through phosphorylation, while IRE1 triggers other cell fate signalling pathways, such as c-Jun N-terminal kinase (JNK) that is also a central mediator of insulin signalling and implicated in insulin resistance." (PMID 29720183, 2018). "Additionally, obesity-related peripheral insulin resistance has been also associated with lower transport of insulin across the blood brain barrier, which would lead to cognitive impairment." (PMID 30159333, 2018). "There is considerable evidence showing that whole grain intake is associated with decreased glucose concentrations and is inversely associated with insulin resistance, suggesting that it is possible to regulate glucose and insulin homeostasis by cereal foods and their constituents." (PMID 29762481, 2018). "In rodents, BPA causes disrupted insulin signalling, insulin resistance, and IGT." (PMID 29593656, 2018). "Insulin signal transduction under basal, normal fed conditions was slightly impaired in aged A1+/-s, however this is unlikely to be a causative factor for impaired glucose tolerance and insulin resistance." (PMID 29364890, 2018). "The question that needs to be addressed is whether O-GlcNAcylation is solely a mediator of diabetic associated glucotoxicity in DC or whether it also disturbs insulin sensitivity and thus promotes cardiac insulin resistance?" (PMID 30420836, 2018). "Takashima22 reported that tau hyperphosphorylation via GSK-3β was associated with insulin resistance in the central nervous system; this suggested, as implied by our study, that impaired brain insulin signaling could contribute to tau hyperphosphorylation." (PMID 29673239, 2018). "Pro-inflammatory cytokines might cause insulin resistance by inhibiting insulin signal transduction." (PMID 31448006, 2018).